TERT (telomerase reverse transcriptase)
Diseases named in the same sentence as TERT in open-access papers (continued):
Sharing a sentence is not in itself a finding about the gene and the disease.
glioma (continued). "To address this, we first determined whether NAF1 expression was regulated by TERT in glioma cells." (PMID 30936423, 2019). "Among the 573 cases of Grade II-IV gliomas, 103 (18.0%) were triple-positive, 19 (3.3%) had mutations in both IDH and TERT, 108 (18.8%) had IDH mutation only, 144 (25.1%) were triple-negative, 155 (27.1%) had TERT mutation only, and 44 (7.7%) had other combinations of the three biomarkers." (PMID 31444316, 2019). "For example, in hepatoblastoma, the most common childhood liver cancer, as well as in pediatric gliomas, acute myeloid leukemia and thyroid cancers, TERT gene or promoter mutations have not been observed or far less frequently than in corresponding adult malignancies." (PMID 31757062, 2019). "Our findings of an unexpected increase in the expression of TERT protein even in the TERT-wildtype gliomas raise the possibility that the expression of TERT mRNA and protein could be regulated by the mechanism other than its promoter mutations, including via epigenetic factors." (PMID 29693015, 2018). "However, the TERT transcripts range widely in expression in various cancers including gliomas, and there may be other potential mechanisms to upregulate TERT mRNA in addition to its promoter mutations." (PMID 29693015, 2018). "In addition to its applicability to the molecular diagnostics of gliomas, TERT could be a good therapeutic target against diffuse gliomas which are a potentially malignant, incurable brain tumor in human." (PMID 29693015, 2018). "The cohort had several clinical and molecular characteristics: age ≥ 80 years (26.4%), lower-grade glioma (18.6%), preoperative KPS scores below 70 (51.4%), resection (34.3%), adjuvant RT + TMZ (68.6%), MGMT promoter methylation (48.6%), IDH1/2 mutation (7.7%) and TERT promoter mutation (60.9%)." (PMID 30076584, 2018). "Immunohistochemistry with this TERT-specific antibody could not play the diagnostic surrogate for TERT promoter mutations, but we could find an unexpected increase in TERT immunoreactivity across all types of gliomas and tumor vasculature." (PMID 29693015, 2018). "Among their series of grade II or III gliomas (N = 586), 40.4% (40/99) of IDH-WT astrocytoma and 10.1% (31/306) of IDH-mutant astrocytoma was TERTp-mutated tumors and remained 181 cases were triple positive (1p/19q co-deleted, IDH-mutant, and TERT-mutated) ODG." (PMID 28851427, 2017). "Therefore, overexpression of TERT is a biomarker for glioma recurrence, prognosis and progression." (PMID 29262650, 2017). "Whether TERT promoter mutations and variable RTL are indeed associated with poor overall survival (OS), as suggested by their association with clinicopathologic features of glioma patients, was subsequently investigated by univariate survival analysis." (PMID 26556853, 2016). "Importantly, we observed that TERT promoter mutations particularly C228T and long telomere length significantly impacted radiotherapy outcome in glioma patients, which appears independent of WHO grade, KPS score, IDH1 mutations and MGMT methylation." (PMID 26556853, 2016). "Importantly, IDH mutated, 1p/19q codeleted gliomas were characterized by mutations in CIC, FUBP1, NOTCH1, and TERT promoter, suggesting these mutations could serve as oligodendroglial lineage markers." (PMID 27556304, 2016). "In previous genome-wide association studies, researchers have shown that genetic polymorphisms in the telomere-related genes TERC, TERT and RTEL1 are related to increased glioma susceptibility, suggesting that telomere may play an important role in glioma genesis." (PMID 27655710, 2016).
glioma (continued). "In this study, we examined the utility of molecular classification based on the IDH and TERT statuses to predict clinical courses of patients in association with various clinical factors, histological diagnosis, and grading in a large series of newly diagnosed WHO grade II-IV adult gliomas." (PMID 27503138, 2016). "TERT promoter mutations were detected only in gliomas and not in other types of brain tumor, indicating that the identified mutations could serve as glioma-specific biomarkers to predicting tumor occurrence or recurrence." (PMID 24937153, 2014). "Although TERT variants have not been previously reported to be associated with ovarian cancer, a recent meta-analysis of two GWAS identified another SNP in TERT, rs2736100, as significantly associated with gliomas (OR = 1.27; P = 1.50×10−17)." (PMID 20628624, 2010). "In gliomas, the overall survival (OS) (10.9 vs. 15.9) and progression-free survival (PFS) (6.9 vs. 12.3) of the TERT promoter mutant group were significantly lower than those of the TERT promoter wild-type group, representing a poorer prognosis." (PMID 39871386, 2025). "We downloaded transcriptomic data of gliomas (WHO grade 2–4) from the TCGA database and divided the samples into two groups based on TERT promoter status." (PMID 40149633, 2025). "Additionally, IDH mutations often co‐occur with glioma‐associated genetic alterations including BRAF, TERT promoter, 1p/19q co‐deletion, and MGMT promoter methylation, which may also result in shifts of metabolic pathways and the spatial heterogeneity of H2O2/GSH ratio." (PMID 40171868, 2025). "Broadly, cancer cells and immortalized cell lines are hypermethylated at CpGs in the core TERT promoter and THOR, including cancers of the central nervous system." (PMID 38837897, 2024). "While patients with highly aggressive IDH wild‐type gliomas have an abysmal prognosis, those with IDH gene and TERT gene promoter comutant tumors receive much greater benefit from current treatments." (PMID 36176070, 2023). "Among the three major glioma subtypes, similar positive correlations were found for MGMT promoter methylation and TERT promoter VAF in IDHwt GBM, and for IDH VAF in both IDHmut astrocytoma (non-significant) and IDHmut oligodendroglioma." (PMID 37919784, 2023). "Gliomas with comutations of isocitrate dehydrogenase (IDH) genes and telomerase reverse transcriptase (TERT) gene promoter (IDHmut pTERTmut) show distinct biological features and respond to first‐line treatment differently in comparison with other gliomas." (PMID 36176070, 2023). "This may mean that the TERT mutation does not correlate with the frequency of seizures in gliomas." (PMID 38067243, 2023).
glioma (continued). "In AGS glioma cases, those with IDH/1p19q/TERT-WT WHO 2016 classification of glioma had r = 0.97 (p < 0.0001), and other AGS glioma cases had r = 0.98 (p < 0.0001)." (PMID 36307860, 2022). "DWI metrics, including nADC and omADC from the solid part of the glioma, have a potential ability to predict tumor grade and IDH-mut, but have limited use in the prediction of TERT-mut and MGMT-m." (PMID 36471242, 2022). "For WHO II-IV gliomas, we found that ADC values had less accuracy and reliability in discriminating MGMT and TERT status, which limited the use of DWI metrics in predicting these two genotypes." (PMID 36471242, 2022). "Material and Method: We identified 84 patients with grade II-IV glioma with IDH, ATRX, 1p / 19q and TERT status." (PMID 34558656, 2022). "For the low-grade gliomas (Grades II-III), TERT-p mutant patients have a better prognosis than the wildtype patients, whereas for the GBMs (Grade IV), TERT-p mutation is related to a poor prognosis." (PMID 35495630, 2022). "To conclude, this study suggest that TERT correlates with immune response and the infiltration of neutrophils in the IDH wild-type glioma microenvironment." (PMID 33996815, 2021). "Cancer-specific molecular characterization papers of liver hepatocellular carcinoma (LIHC), lower grade glioma (LGG), and glioblastoma multiforme (GBM) have described mechanisms for their subtype-dependent differences in TERT expression." (PMID 33924498, 2021). "Among these, one region on chromosome 5p15.33 harboring the TERT and CLPTM1L genes had statistically significant shared heritability for seven cancer types, including ER-negative breast, colorectal, glioma, lung, melanoma, pancreatic, and prostate cancer." (PMID 34355204, 2021). "A prognostic risk model was constructed according to four selected AGs (LEP, TERT, PON1, and SSTR3) in the TCGA dataset and Chinese Glioma Genome Atlas (CGGA) database." (PMID 34114970, 2021). "The four selected AGs (LEP, TERT, PON1, and SSTR3) were concluded to have important functions in immune cell infiltration of glioma." (PMID 34114970, 2021). "DH1, TERT, EGFR, PTEN, ATRX and other key factors are expressed in gliomas as in human GBM, and EGFR is upregulated in tree shrew GBM." (PMID 33768009, 2021). "Inversely, down-regulated TERT expression was coincided with declined expression of EGFR, basic fibroblast growth factor (bFGF) and glioma stem cell properties." (PMID 33869033, 2021). "A study for gliomas patients by detecting of IDH1, TERT, and H3K27M also showed high detection sensitivity (71%, 20 out of 28) and specificity." (PMID 34603383, 2021). "Another biomarker, Telomerase Reverse Transcriptase (TERT), has been validated for diagnosis in gliomas patients, with overall 62.5% sensitivity and 90% specificity." (PMID 34603383, 2021). "However, in these studies, TERT mRNA expression was used as a surrogate for TERT mutational status in a considerable number of cases and, therefore, were not conclusive in their evaluation of the value of TERT promoter mutation as an independent prognostic marker in IDH-mutated gliomas." (PMID 33228806, 2020). "Acknowledging minimal heterogeneity, we believe that our meta-analysis provides robust and useful directionality regarding the potential interaction between TERT and MGMT in glioma patients." (PMID 32957941, 2020).
glioma (continued). "A previous study suggested that TERT gene expression and telomerase activity are down-regulated in somewhat TMZ-sensitive glioma cells, whereas the inhibitory effect of TMZ against telomerase is weakened in TMZ-resistant glioma cells." (PMID 32528873, 2020). "In vitro, overexpression of IDHR132H in the glioma cell line LN319 resulted in downregulation of ATRX and rapid TERT-independent telomere lengthening consistent with ALT." (PMID 31960234, 2020). "The BRAF gene and the TERT promoter are among the most frequently altered genomic loci in low-grade (LGG) and high-grade-glioma (HGG), respectively." (PMID 31391125, 2019). "Evidently, the overall survival of glioma patients can be affected by many important clinical and genetic factors, such as age, tumor grades, ATRX status, IDH1/2 status, telomerase reverse transcriptase (TERT) status, and so on16,17." (PMID 30936423, 2019). "Altogether, our data suggest that NAF1 lengthens telomere length through regulating TERT at both transcription and translation levels and TERC at transcription levels in glioma cells." (PMID 30936423, 2019). "Mechanistically, NAF1 maintains telomere length through regulating two major components of telomerase, TERT and TERC37, at transcription and/or translation levels, thereby contributing to malignant progression of gliomas." (PMID 30936423, 2019). "Thus, we supposed that TERT may be involved in regulating NAF1 transcription in glioma cells." (PMID 30936423, 2019). "Another study that attempted to further sub-classify the 5 integrated WHO glioma groups by ATRX and TERT promoter status showed that ATRX alterations were enriched in TERTp-wt GBM." (PMID 30333046, 2018). "Additional prognostic roles of TERT and ATRX were recently demonstrated for adult infiltrating gliomas with WHO 2016 diagnosis." (PMID 28513547, 2017). "Taken together, these findings suggest that Nrf2-driven TERT has a crucial role in regulating PPP and glycogen accumulation in glioma cells." (PMID 27148686, 2016). "Compared with the TERT, Survivin, Cox2 and E2F1 promoters, the transcriptional activity of the FOS promoter was higher in all three glioma cell lines.." (PMID 26571389, 2015). "Compared with TERT, Survivin, Cox2 and E2F1 promoter, the transcriptional activity of FOS promoter was higher in glioma cell lines." (PMID 26571389, 2015). "In this study, we compared the transcriptional activities of FOS, TERT, Survivin, E2F1, Cox2 and CMV promoter in human glioma lines." (PMID 26571389, 2015). "Similarly, the favor prognosis of TERT promoter mutation in CDKN2A/B none homozygous deletion IDH mutant adult‐type gliomas, which the difference with the CDKN2A/B homozygous deletion group may be caused by the limited number of CDKN2A/B homozygous deletion group." (PMID 39804195, 2025). "Although not directly applicable to non-mutant TERT promoter gliomas (i.e., 40% of gliomas), this study delivers an important proof-of-concept regarding cfDNA as a blood-based monitoring marker in glioma." (PMID 40285800, 2025). "As a result, GABPB1 is now considered a promising target for inhibiting TERT and treating gliomas without toxicity." (PMID 40463649, 2025). "Eleven glioma cases were classified as glioma NOS because genetic analysis showed no IDH1/2, TERT promoter, or H3-3A mutations." (PMID 41163986, 2025).
glioma (continued). "NEC gliomas are IDH1 non-mutant gliomas that express ATRX, lack necrosis or microvascular proliferation, and do not have chromosome 7 gain, chromosome 10 loss, EGFR amplification, or TERT promoter mutation." (PMID 39135755, 2024). "Glioblastoma is a glial tumor that is IDH1 non-mutant with necrosis and/or microvascular proliferation or with chromosome 7 gain and chromosome 10 loss or EGFR amplification or TERT promoter mutation." (PMID 39135755, 2024). "EGFR amplification was also observed to be limited to IDH wildtype (26%) and TERT mutant (27%) gliomas, occurring irrespective of MGMT promoter methylation status and being mutually exclusive with 1p/19q co-deletion (LOH)." (PMID 38893240, 2024). "The upregulation of TERT expression and resulting telomerase activity appears in the majority of human malignancies and are related to tumor progression and aggressiveness, including HCC, melanoma, urothelial carcinoma, glioma, and thyroid cancer." (PMID 38572921, 2024). "For instance, the prognostic implications of an IDHmut glioma with both 1p/19q codeletion, which is beneficial, and TERT wildtype, which is not, raises the question of which markers or combinations thereof most significantly affect survival." (PMID 38982347, 2024). "In addition to IDH1/2 mutation, MGMT promotor methylation, EGFR amplification, TERT promotor mutation, and CDKN2A/B homozygous deletion, we sought to elucidate the alterations of other potential molecular biomarkers that might provide clues for clinical decision-making in gliomas." (PMID 36998447, 2023). "Unlike adult low-grade gliomas that are characterized by robust molecular alterations such as IDH mutations, 1p/19q codeletion, and TERT promoter mutations, PLGGs harbor their own molecular alterations distinct from adult counterparts." (PMID 37697238, 2023). "The roles of non-canonical NF-κB signalling and ETS1 have both been well documented to regulate glioma migration, invasion and cell proliferation Furthermore, p52 and ETS1 have been described to function cooperatively at the mutant TERT promoter to drive telomerase expression in gliomas." (PMID 37087499, 2023). "We hypothesized that coexisting factors or interactions between variables might induce the increment of ADC in TERT-wt and MGMT-m gliomas." (PMID 36471242, 2022). "Fourth, some important glioma-related biomarkers like O6-methylguanine-DNA methyltransferase (MGMT) methylation and telomerase reverse transcriptase (TERT) mutation status were not included in the study due to incomplete pathological information." (PMID 36052263, 2022). "None of the 47 NF1-associated gliomas in this cohort had IDH1 or IDH2 mutation, EGFR amplification, TERT promoter mutation, or histone H3 p.G34 mutation." (PMID 35945463, 2022). "Conventional structural magnetic resonance imaging (MRI) features, including glioma location, glioma volume, necrosis, invasiveness, enhancement pattern, and peritumoral edema, have been used to predict the IDH, MGMT, and TERT status, however with controversies." (PMID 36471242, 2022). "Of IDH wildtype and TERT mutant gliomas, 58.13% were EGFR non-amplified and 41.87% were EGFR amplified." (PMID 35453544, 2022).